IL17A (interleukin 17A)
Diseases named in the same sentence as IL17A in open-access papers (continued):
Sharing a sentence is not in itself a finding about the gene and the disease.
psoriasis (continued). "Ixekizumab (Taltz®) is a humanized anti-IL-17A monoclonal antibody approved for the treatment of various inflammatory diseases including psoriasis and psoriatic arthritis." (PMID 37371813, 2023). "Elevated H3K9 and H3K27 acetylation in the IL17A promoter region in immune cells of psoriatic patients have been observed, leading to Th17 differentiation and psoriasis development." (PMID 37628670, 2023). "TH17 lymphocytes, differentiating under the influence of dendritic cell-derived IL-23, and mediating their effects via IL-17A, are believed to be central effector cells in psoriasis." (PMID 37283755, 2023). "In conclusion, anti-IL36R treatment is not only able to prevent the development of IL17A-driven psoriasis but also to inhibit and partially resolve psoriatic lesions and associated psoriasis-associated systemic inflammation." (PMID 38162658, 2023). "Cytokines such as IL-17A, IL-17E, IL-4 and IL-36γ regulate the inflammatory responses in keratinocytes in both AD and psoriasis." (PMID 36271146, 2022). "It was reported that HLA-C-presented melanocyte was attacked by CD8± T cells and further induced T cells to secrete IL17A in psoriasis lesions." (PMID 35774389, 2022). "When moderate-to-severe psoriasis patients were treated with IL-17A monoclonal antibody (secukinumab) for 52 weeks and then stopped the medication, 84% of patients experienced relapse of psoriasis within the next 52 weeks." (PMID 36110854, 2022). "Th17 cell expression in inguinal lymph nodes and IL-17A secretion was suppressed by forsythoside A. In conclusion, forsythoside A was found to alleviate imiquimod-induced psoriasis-like dermatitis in mice by suppressing Th17 development and IL-17A secretion." (PMID 35055377, 2022). "The mechanism of action of ixekizumab is similar to that of secukinumab, which involves targeting IL-17A in psoriasis pathogenesis." (PMID 35203707, 2022). "And the activation and upregulation of IL17A in psoriatic skin produces a “feed forward” effect further contributing to sustain a vicious cycle of inflammation in psoriasis." (PMID 35922852, 2022). "In the pathogenesis of psoriasis, epidermal keratinocytes produce various inflammatory cytokines and chemokines, leading to the recruitment of immune cells, such as IL-17A-producing cells and neutrophils." (PMID 35457132, 2022). "Consistent with the ameliorated psoriasis‐like phenotype, the mRNA levels of genes related to the IL‐23/IL‐17 axis, such as Il23a, Il17a, and Il22, and the expression of Tnfa, Il6, and Il1b was decreased in the skin." (PMID 34936223, 2022). "Ixekizumab is a human monoclonal antibody directed against IL-17A approved for the management of moderate-severe psoriasis in adults and of psoriatic arthritis." (PMID 35741329, 2022). "In this study, we developed an in vitro psoriasis-like reconstructed human skin equivalent model using only human-derived cells and extracellular matrix and adding IL-17A." (PMID 35745784, 2022). "In inflammatory conditions such as psoriasis, mast cells that release MCETs also release large quantities of IL-17a, a proinflammatory cytokine which recruits neutrophils." (PMID 35409152, 2022). "As well as in psoriasis, the enrichment of IL-17A-producing immune cells leads to produce high levels of IL-17A, which further stimulates keratinocytes producing CCL20, CXCL8, and IL-36γ to recruit more IL-17A-producing immune cells and neutrophils." (PMID 35069008, 2022). "First, an IL-17A-neutralizing antibody was used to validate that the PS+T model responded appropriately to a known psoriasis treatment (PS+T+IL-17A mAb)." (PMID 36139479, 2022). "In psoriasis patients receiving anti‐IL‐17A treatment, expression of NFKBIZ and IL36G are positively correlated." (PMID 36245291, 2022). "Many relevant psoriasis markers including IL-17A and IL-17C were enriched in this blood transcriptome study." (PMID 35682804, 2022).
psoriasis (continued). "ndSTAT1-TMD specifically inhibited the transcriptional activity of endogenous STAT1 in Th1 and Th17 cells and showed a therapeutic potential comparable to that of anti-IL-17A antibody when administered to psoriasis and IBD mouse models." (PMID 36591260, 2022). "The importance of the TNF-α and IL-23/IL-17A axis in disease pathogenesis is well described for psoriasis and psoriatic arthritis." (PMID 35203534, 2022). "The increased production of IL-17A and IFNγ in the supernatant of PS+T was also validated, confirming the evidence of the pro-inflammatory microenvironment specific of psoriasis." (PMID 36139479, 2022). "E. Secukinumab, a monoclonal antibody directly targeting IL17A, is an approved treatment for psoriasis." (PMID 35563285, 2022). "Patients with psoriasis who show high levels of cytokines, Th17 cells and IL-17A, are more subjected to develop depression and anxiety disorders." (PMID 35335319, 2022). "In this work, clinical trial data from two monoclonal antibodies (mAbs) targeting IL-17A for treatment of psoriasis (secukinumab and ixekizumab) were analyzed simultaneously to quantitatively predict their target engagement (TE) profiles in psoriatic skin." (PMID 35548359, 2022). "Secukinumab and Ixekizumab inhibit IL-17A and IL-17A/F and can be used in the treatment of autoimmune diseases like psoriasis." (PMID 35603223, 2022). "We further analyzed the correlation between the expression of these regulators and some well-known gene biomarkers of psoriasis (i.e. IL17A, IL17C, IL23A) and measures of disease severity (i.e. the PASI and PSI)." (PMID 35874668, 2022). "It has been reported that the CCL20/CCR6 axis contributes to the formation of an IL17A-rich milieu in psoriasis." (PMID 35774389, 2022). "Psoriasis is labeled as an IL-17A-driven disease; however, IL-17C, IL-17E as well as IL-17F also contribute to this pathology." (PMID 36140808, 2022). "BD‐2 is a biomarker of IL‐17A‐driven pathology in psoriasis and S100A7 is associated with the severity of HS disease (Hurley staging), making these mediators useful surrogate markers of downstream IL‐17 activity." (PMID 35638561, 2022). "The double-blind, randomized, placebo-controlled phase 3 IXORA-PEDS study addressed the high-affinity monoclonal antibody to IL-17A ixekizumab in pediatric psoriasis." (PMID 36232430, 2022). "In the literature, several studies have appeared investigating serum levels of IL-17A in psoriasis and controls and the results reported are controversial." (PMID 35340911, 2022). "Among them, TNF-α, IL-17A, and IL-23 are of central importance in psoriasis as therapies targeting them are most efficient in the treatment of patients." (PMID 35075118, 2022). "The therapeutic efficacy of anti-TNF-α/IL-23/IL-17A biologics for psoriasis suggests that the TNF-α/IL-23/IL-17A axis plays a central role in its pathogenesis." (PMID 35663970, 2022). "Interleukin (IL)-17A is an inflammatory cytokine that plays a key role in the pathogenesis of psoriasis." (PMID 35548359, 2022). "The level of circulating EVs expressing IL-17A was higher in patients with moderate-to-severe psoriasis than in those with mild psoriasis." (PMID 35769256, 2022). "Although several monoclonal antibodies targeting IL-17A or its receptors have been used to treat psoriasis, the incidence of Candida infections in patients treated with these antibodies is increased." (PMID 35805960, 2022). "In keratinocytes, induction of GLS1 was caused by IL-17A/MALT1/c-Jun axis, and enhanced cell proliferation and chemokine production, contributing to the development of psoriasis phenotype." (PMID 35075118, 2022). "IL-17A is an inflammatory cytokine secreted by Th17 cells and is reported to play a key role in the pathogenesis of psoriasis." (PMID 35548359, 2022). "Despite the well-evidenced therapeutic efficacy of biologic agents targeting IL-17A, several studies found comparable levels of IL-17A between psoriasis and healthy donors." (PMID 36118416, 2022).
psoriasis (continued). "It is generally accepted that interleukin-23 (IL-23)/interleukin-17A (IL-17A) axis plays a pivotal role in the psoriasis etiology." (PMID 36033390, 2022). "In line with earlier findings of increased frequencies of IL-17A and IL-22 producing cells in psoriasis and PsA, we also found increased numbers of Th17 cells (metaclusters 1) in both psoriasis and PsA patients compared to healthy controls." (PMID 35045868, 2022). "Mechanically, epidermal IL-17E expression is upregulated by IL-17A in psoriasis, and through its receptor IL-17RB on keratinocytes, it promotes keratinocyte proliferation and production of inflammatory cytokines and chemokines via STAT3 activation." (PMID 35075118, 2022). "Accordingly, administration of IL-17A had effects similar to psoriasis-like inflammation on neurobehavioral and NFκB/p38MAPK pathways, while blockade of both NFκB and p38MAPK reduced IL-17A levels associated with depression-like behavior." (PMID 36189272, 2022). "The investigation of serum IL-17A in psoriasis patients revealed the increment of IL-17A, indicating a more highly lesioned microenvironment." (PMID 35203707, 2022). "Nowadays, the therapeutic biological agents of psoriasis usually target the core pathway: IL-23/IL-17A-Th17 axis." (PMID 35277199, 2022). "Dual-color immunofluorescence showed that IL-17A+ neutrophils considerably outnumbered IL-17A+ T cells in the lesional skin, suggesting neutrophils as an abundant source of IL-17A in psoriasis." (PMID 35401573, 2022). "IL-17A is a cytokine secreted by Th17 cells and is abundantly found in the lesions of patients with psoriasis." (PMID 35055377, 2022). "In three murine experimental models of psoriasis-like skin disease, levels of IL-17A correlated with the severity of the disease and vascular dysfunction." (PMID 35313642, 2022). "Secukinumab and Ixekizumab are two biological agents clinically available for psoriasis, which can relieve inflammation by selectively binding to IL-17A." (PMID 35055377, 2022). "A mixture of five inflammatory molecules (TNF-α, IL-1α, IL-17A, IL-22, and oncostatin M; 10 ng/mL each) was used to stimulate HaCaT cells to mimic the microenvironment of psoriasis." (PMID 35209199, 2022). "The median number of transcript-positive cells per section for IFNG, IL13, and IL17A mRNA were 83, 4 and 11 for LP, AD, and psoriasis, respectively, thus confirming our observations from the ST analysis." (PMID 36513651, 2022). "Under the condition of abundant IL-23 in psoriasis lesional skin, some macrophages possibly produce IL-17A, IL-22 and IFN-γ in addition to TNF-α." (PMID 35837394, 2022). "IL-17A overexpression is consistently detected in psoriatic lesions and therapeutic antibodies against IL-17A achieve great success in treating psoriasis, suggesting a pivotal role of IL-17A in psoriasis pathogenesis." (PMID 36118416, 2022). "Drugs targeting the IL-17A cytokine and its signaling pathway have shown effectiveness in treatment of psoriasis and other immune disorders." (PMID 35548359, 2022). "Interleukin-17A (IL-17A) is a key mediator of protective immunity to yeast and bacterial infections but also drives the pathogenesis of several autoimmune diseases, such as psoriasis or psoriatic arthritis." (PMID 36271145, 2022). "One of the sources of IL-17A in psoriasis is Th17 cells, then they are stimulated to secrete further cytokines by IL-23, which include (besides IL-17A): IL-17F, IL-21, IL-22, IL-26, and TNF-α." (PMID 36226313, 2022). "(2017) reported that the treatment with a high-affinity monoclonal antibody to IL-17A ixekizumab reduced depressive symptoms in patients with psoriasis." (PMID 36189272, 2022). "Hes1 was also reported to regulate IL-17A+γδ+ T cell expression and IL-17A secretion in mouse psoriasis-like skin inflammation." (PMID 36535970, 2022).
psoriasis (continued). "T‐cell subsets, Th17, and γδT cells are reported to produce IL‐17A in other skin diseases (e.g. psoriasis), which in turn can elicit a signalling cascade in the epidermis and dermis." (PMID 35638561, 2022). "Consistently, IL-17A in supernatants was higher when HaCaT cells were cultured with neutrophils from psoriasis patients than those from controls." (PMID 35401573, 2022). "The use of anti-IL10 antibodies was also assayed in other inflammatory diseases, including psoriasis lesions; anti-IL10 antibody treatment upregulates IL-17A, which plays a central role in psoriasis pathogenesis." (PMID 36297479, 2022). "The TNF/IL23/IL17A axis was also widely involved in the body's immune response, promoting the occurrence of psoriasis inflammatory response and the proliferation of epidermal cells." (PMID 35265149, 2022). "The mPBPK model for secukinumab and ixekizumab IL-17A TE was developed by fitting data reported from clinical trials conducted in psoriasis patients." (PMID 35548359, 2022). "Several biologics, including anti-IL-23 (p40-specific ustekinumab and p19-specific guselkumab) and anti-IL-17A (secukinumab), has been approved to treat psoriasis." (PMID 35637050, 2022). "Netakimab is a humanized IgG1 monoclonal antibody against IL-17a that was registered in Russia in spring 2020 for the treatment of psoriasis, ankylosing spondylitis (ClinicalTrials.gov: NCT03447704), and psoriatic arthritis (ClinicalTrials.gov: NCT03598751)." (PMID 36001576, 2022). "KCs are also the main cell type expressing the IL-17 receptor in psoriasis, and IL-17A increases the expression of pro-inflammatory cytokines, chemokines, and antimicrobial peptides (AMPs) in KCs19,20." (PMID 35869084, 2022). "It has been shown that the connections between periodontitis and several inflammatory diseases such as psoriasis, rheumatoid arthritis, and inflammatory bowel diseases are mediated by intestinal IL-17A." (PMID 35663549, 2022). "It is noteworthy that IL‐17A and TNFα were primarily considered as stimulants of IκBζ‐executed psoriasis‐like skin lesions; however, the search for additional IκBζ inducers was pursued." (PMID 36245291, 2022). "ROC curve analysis indicated the serum IL-17A, serum Claudin-1, and combination of IL-17A and serum Claudin-1 for predicting psoriasis with the areas under the curve (AUC) of 0.951 (p < 0.0001), 0.709 (p = 0.0119), and 0.949 (p < 0.0001), respectively." (PMID 35340911, 2022). "Guselkumab TremfyaTM, used for the treatment of psoriasis and Psa, is an antibody that blocks the activity of two interleukins (IL-23, IL-17A) that are overexpressed in these diseases." (PMID 36140426, 2022). "Most of these molecules were acute-phase proteins involved in IL-17A signaling in autoimmune diseases such as psoriasis and arthritis (14.3% overlap; P = 0.0000266)." (PMID 35592852, 2022). "The function of Th17 cells and IL-17A, the signature cytokine of Th17 cells, are pivotal for the development of psoriasis." (PMID 36314037, 2022). "Previous studies reported that dermal γδ T cells are the main source of IL-17A in the skin lesions of IMQ-induced psoriasis-like mice." (PMID 35922852, 2022). "In psoriasis, IL-17A directly enhances keratinocyte gene expression, such as that of cathelicidin (LL-37) antimicrobial peptides, via its target receptors, IL-17RA and IL-17RC." (PMID 35203707, 2022). "Our present study showed the success of IMQ-induced psoriasis as a model to study the IL-23/IL-17A axis." (PMID 36620087, 2022). "MBMA of clinical trial data for two marketed anti-IL-17A drugs was coupled with mPBPK modeling to understand the relationship between IL-17A suppression in skin and clinical efficacy in psoriasis patients." (PMID 35548359, 2022). "IL-17A is shown to be one of the major drivers for several inflammatory and autoimmune diseases like multiple sclerosis, psoriasis, asthma, Crohn’s disease and rheumatoid arthritis." (PMID 36195874, 2022).
psoriasis (continued). "Anti-IL17A therapies have proven effective for numerous inflammatory diseases including psoriasis, axial spondylitis and psoriatic arthritis." (PMID 36028520, 2022). "Both keratinocytes and immune cells contribute to the pathogenesis of psoriasis, and IL-23 and IL-17A were identified as key drivers of this immune process." (PMID 36419191, 2022). "In our current study, combinatorial biomarkers of serum IL-17A and Claudin-1 are potential predictive markers for psoriasis and Claudin-1 for identification onsets of psoriasis, although little is known about the role of Claudin-1 in the age at onset." (PMID 35340911, 2022). "Biological agents, specifically anti IL-17A, anti-IL-23, and anti p-40 agents, have been shown to be effective against psoriasis in recent years." (PMID 36590975, 2022). "It has been shown that mAbs generated against the proinflammatory cytokine IL-17A are highly effective against psoriasis, which affects between 1 and 4% of global populations." (PMID 35962190, 2022). "Currently, anti-inflammatory monoclonal antibody therapies, such as anti-IL17a, have been used to effectively treat psoriasis patients." (PMID 35769463, 2022). "We found that the mRNA and pro-/mature protein levels of IL-1β, another important cytokine in psoriasis, were significantly increased after stimulation with IL-17A and TNF-α." (PMID 35153790, 2022). "The ‘‘IL-23-IL-17 axis’’ is also suggested to be a key driver and IL-23 and IL-17A are critical mediators of autoimmune diseases like psoriasis." (PMID 35603223, 2022). "Psoriasis expressed preferential Th17 skewing, with a significant increase in Th17-related factors (IL-17A/F and IL-36A/G)." (PMID 36465933, 2022). "Secukinumab, a recombinant, fully human IL-17A inhibitor, has been approved for the treatment of pediatric psoriasis patients aged ≥6 years in both the USA and Europe." (PMID 36160145, 2022). "In a preclinical model of psoriasis, the dermal overexpression of IL-17A induces vascular oxidative stress and arterial hypertension." (PMID 36012327, 2022). "Among inflammatory cytokines, interleukin-17A (IL-17A) plays a pivotal role in the pathogenesis of psoriasis." (PMID 35922852, 2022). "Unexpectedly, neutrophils from both healthy donors and psoriasis patients similarly activate keratinocytes despite higher expression of IL-17A in psoriatic neutrophils." (PMID 35401573, 2022). "In support of the Role of IL-17A in the Psoriasis Pathway, CXCL1, CXCL3, CXCL6, S100A8, S100A9, and CCL20 in the shared signature were all upregulated in both psoriatic skin and colon lesional tissues." (PMID 36396672, 2022). "Recently, however, there has been a paradigm shift in the understanding of cellular sources of IL-17A in psoriasis." (PMID 35401573, 2022). "IL-23/IL-17A axis plays an important role in skin inflammation and autoimmune diseases, including psoriasis." (PMID 36389696, 2022). "Brodalumab, a human monoclonal antibody against IL-17RA, which mediates the downstream signaling of IL-17A, IL-17F, IL-17A/F, IL-17C, and IL-17E, has been approved for the treatment of psoriasis." (PMID 35626662, 2022). "Secukinumab is a human monoclonal IgG1 k antibody that was developed to block the actions of IL-17A.6, 7, 8, 9 In 2015, an anti-IL-17 was approved for the first time, for the treatment of moderate-to-severe psoriasis and psoriatic arthritis in adult patients." (PMID 35843765, 2022). "IL-17A plays a crucial role in psoriasis by stimulating the differentiation and proliferation of keratinocytes." (PMID 35055377, 2022). "Maternal psoriasis has recently received attention because IL-17A is one of the most important cytokines in the pathogenesis of psoriasis." (PMID 35211045, 2022). "Given thesuccess of the marketed antibody drugs secukinumab (Cosentyx) andixekizumab (Talz) in psoriasis, psoriatic arthritis, and ankylosingspondylitis, the race to a commercial small-molecule IL-17a antagonisthas started." (PMID 36105327, 2022).